SUMO3 (small ubiquitin like modifier 3)
Description:
Ubiquitin-like protein which can be covalently attached to target lysines either as a monomer or as a lysine-linked polymer. Does not seem to be involved in protein degradation and may function as an antagonist of ubiquitin in the degradation process. Plays a role in a number of cellular processes such as nuclear transport, DNA replication and repair, mitosis and signal transduction. Covalent attachment to its substrates requires prior activation by the E1 complex SAE1-SAE2 and linkage to the E2 enzyme UBE2I, and can be promoted by an E3 ligase such as PIAS1-4, RANBP2 or CBX4. Plays a role in the regulation of sumoylation status of SETX.
Synonyms: SUMO-3; Smt3A; SMT3H1
Tractability: Small molecule: a structure with a bound ligand is known. PROTAC: UniProt records ubiquitination sites on it; ubiquitination databases record sites on it; its protein half-life has been measured; a small molecule that binds it is known.
Gene: Protein-coding gene on chromosome 21 (44,805,617 to 44,818,779, reverse strand). Ensembl gene ENSG00000184900.
Subcellular location: Cytoplasm; Nucleus; Nucleus, PML body
Subcellular location (Human Protein Atlas): Nuclear bodies; Nucleoplasm; Calyx; Connecting piece; Flagellar centriole
Pathways (Reactome):
Metabolism of proteins: SUMO is conjugated to E1 (UBA2:SAE1); SUMO is proteolytically processed; SUMO is transferred from E1 to E2 (UBE2I, UBC9); SUMOylation of DNA damage response and repair proteins; SUMOylation of DNA replication proteins; SUMOylation of chromatin organization proteins; SUMOylation of immune response proteins; SUMOylation of intracellular receptors; SUMOylation of transcription cofactors; SUMOylation of transcription factors
DNA Repair: Formation of Incision Complex in GG-NER
Gene Ontology:
Molecular function: protein binding; protein tag activity; ubiquitin-like protein ligase binding; SUMO transferase activity
Biological process: protein sumoylation; regulation of protein localization to nucleus
Cellular component: nuclear body; nucleoplasm; nucleus; PML body; kinetochore; cytoplasm; glutamatergic synapse; postsynaptic cytosol; presynaptic cytosol
Genetic constraint (gnomAD): Loss-of-function variants: 2 observed, 11.29 expected, observed/expected ratio (o/e) 0.18, 90% interval 0.071 to 0.56. The upper end of that interval is the gene's LOEUF score, 0.56, which puts it in group 2 of 6, group 1 being the genes least tolerant of losing a copy. Missense variants: 70 observed, 135.34 expected, observed/expected ratio (o/e) 0.52, 90% interval 0.43 to 0.63. Synonymous variants: 56 observed, 56.1 expected, observed/expected ratio (o/e) 1, 90% interval 0.8 to 1.25.
Homologues: Orthologues: mouse Sumo3 (89% identical), rat Sumo3 (89% identical), guinea pig SUMO3 (88% identical), pig SUMO3 (88% identical), zebrafish sumo3b (88% identical), zebrafish sumo3a (87% identical), tropical clawed frog sumo2 (82% identical), Drosophila melanogaster Sumo (62% identical). Paralogues in human: SUMO2 (88% identical), SUMO4 (76% identical), NFATC2IP (29% identical).
Diseases named in the same sentence as SUMO3 in open-access papers:
SUMO3 is named in the same sentence as 33 diseases in open-access papers, as found by Europe PMC text mining. Sharing a sentence is not in itself a finding about the gene and the disease. The quoted sentences say what the papers report.
viral infection (5 papers, 2018 to 2025). "SUMO1 expression results in a gain of PKR activity by increasing its activation whereas SUMO3 abrogates its activation upon poly(I:C) transfection or viral infection." (PMID 29352251, 2018). "We individually knocked out SUMO1, SUMO2, or SUMO3 in donor cells (293T) or target cells (A549-hACE2), to determine the impact of SUMOylation on Spike function during protein synthesis or viral infection." (PMID 40521184, 2025). "The precise inhibitory mechanism of IFITMs on viral infection and replication still requires further exploration but their elevated expression by SUMO3 in response to IFN could enhance their antiviral response." (PMID 33968942, 2021). "Interestingly, transgenic Arabidopsis plants overexpressing SUMO3 also show fewer infection symptoms, suggesting a dual role of SUMO3 in allowing viral infection (as a host factor) and activating defense mechanism." (PMID 34485289, 2021). "However, this increase in SUMO3 could also potentially trigger adverse effects on the viral infection since NPR1 SUMOylation promotes the expression of PR genes." (PMID 39689138, 2024). "Remarkably, SUMO1 and SUMO3 expression exert a differential effect on PKR activation SUMO1 expression alone results in PKR and eIF-2α phosphorylation, whereas SUMO3 reduces PKR and eIF-2α phosphorylation upon viral infection or dsRNA transfection." (PMID 33968942, 2021). "Taken together, our results show that SUMO1 and SUMO3 exert differential effects on PKR localization, protein expression and activation in human cells in response to dsRNA or viral infection." (PMID 29352251, 2018). "Based on our findings, we suggest that SUMO3 conjugation to PKR reduces its activation and PKR-mediated phosphorylation of eIF-2α upon poly(I:C) transfection or viral infections." (PMID 29352251, 2018). "Nevertheless, as described for the role of SUMO in the response to bacteria, this scenario is more complex since any impact in SUMO homeostasis produced by altering the levels of SUMO3 has a negative effect on viral infection." (PMID 39689138, 2024). "Interestingly, SUMO1 expression alone resulted in PKR and eIF-2α activation, whereas SUMO3 reduced PKR and eIF-2α activation upon viral infection or dsRNA transfection." (PMID 29352251, 2018). "Importantly, SUMO1 by inducing PKR activation in the absence of viral infection and SUMO3 by counteracting both PKR activation and stability upon EMCV infection shed a new light on the differential effects of SUMO paralogs." (PMID 33968942, 2021). "In addition, SUMO1 expression activated PKR without virus infection demonstrating a gain-of-function, whereas SUMO3 expression reduced its activation upon viral infection or synthetic dsRNA, poly(I:C), transfection." (PMID 29352251, 2018). "Importantly SUMO1, by inducing PKR activation in the absence of viral infection, and SUMO3, by counteracting both PKR activation and stability upon viral infection, shed a new light on the differential effects of SUMO-modified PKR." (PMID 29352251, 2018).
ovarian carcinoma (3 papers, 2021 to 2023). A malignant neoplasm originating from the surface ovarian epithelium. "miR-509-3p inhibited ovarian cancer cell growth, invasion ability, and enhanced their chemosensitivity by downregulating SUMO-3." (PMID 37386587, 2023). "Here, we provide evidence that a novel miR-509-3p epigenetic silencing alternation and SUMO-3 targeting reduce ovarian cancer cell aggressiveness and chemoresistance." (PMID 37386587, 2023). "These assays found that SENP1 mRNA was highly upregulated, while SUMO3 level was decreased in platinum-resistant ovarian cancer cells (IGROV1 CR), suggesting a possible role of SENP1 in the regulation of platinum-resistance via SUMOylation in ovarian cancer." (PMID 33795649, 2021). "The miR-509-3p/DNMT1/SUMO-3 axis may be an ovarian cancer treatment target." (PMID 37386587, 2023). "Western blot analysis revealed that miR-509-3p overexpression significantly reduced the expression of SUMO-3 in A2780CP70 and OVCAR-8 ovarian cancer cells, whereas miR-509-3p inhibitors noticeably increased the expression of SUMO3 in A2780 and OVCAR-3 cells." (PMID 37386587, 2023).
heart failure (2 papers, 2022 to 2024). Inability of the heart to pump blood at an adequate rate to meet tissue metabolic requirements. "On the other hand, SUMO2 and SUMO3 expression were found to be elevated in human patients with heart failure, and transgenic overexpression of SUMO2 in experimental models resulted in cardiomyopathy-associated heart failure." (PMID 39596076, 2024).
hepatocellular carcinoma (2 papers, 2015 to 2020). A malignant tumor that arises from hepatocytes. "To explore the association between SUMO2/3 and p65, we over-expressed SUMO2 and SUMO3 in hepatoma cells, respectively." (PMID 26458400, 2015). "To this end, we co-expressed UBL proteins (i.e., MYC-DDK-tagged SUMO-1, HA-tagged SUMO-2, HA-tagged SUMO-3, and MYC-DDK-tagged ISG15) with tagged HBc (i.e., FLAG-tagged or HA-tagged, depending on the used UBL protein) in Huh7 hepatocellular carcinoma cells." (PMID 33256078, 2020).
Obesity (2 papers, 2021 to 2023). Accumulation of substantial excess body fat. "Out of the 5 genes identified as optimal predictors, 3 (ie, CDIPT, MRC2, and SUMO3) have been previously shown to be associated with T2D or obesity." (PMID 37040172, 2023). "Using microarray-based comparative genomic hybridization, another study found deleted SUMO3 in an identified CNV in a child with syndromic obesity." (PMID 37040172, 2023). "SUMO3 has been found to be involved in disorders like obesity and neurodegenerative disorders like Parkinson disease and amyotrophic lateral sclerosis." (PMID 37040172, 2023). "MED25 was previously shown to play a critical role in the endoplasmic reticulum stress response Here, a number of the DEPs identified in the current work, including TSPAN8, SUMO3, INSL3, and MED25, were implicated in obesity-related infertility or subfertility." (PMID 34016141, 2021).
prostate carcinoma (2 papers, 2016 to 2019). A carcinoma that arises from epithelial cells of the prostate gland. "We assessed the potential effect of SUMO3 modification on AR intracellular localization by immunostaining in AR-negative prostate cancer DU145 cells, and detected the effect of PIAS1/SUMO3 overexpression on AR sumoylation related degradation." (PMID 31752909, 2019). "SUMO3 has also been found to enhance Androgen Receptor (AR) transcription independent of sumoylation mechanism in prostate cancer cells." (PMID 27767176, 2016).
renal fibrosis (2 papers, 2024). A final common manifestation of a wide variety of chronic kidney diseases characterized by glomerulosclerosis and tubulointerstitial fibrosis. "By screening genes through databases related to renal fibrosis, two core genes, SUMO3 and CD74, were identified to have a causal relationship with DKD, highlighting their strong predictive accuracy in the validation dataset." (PMID 39398062, 2024). "Sumo3, as a downstream target of β-catenin, could be a potential therapeutic target in fighting against renal fibrosis." (PMID 39438470, 2024). "This further suggested that Sumo3-mediated LKB1 Sumoylation plays a key role in regulating fatty acid metabolism and alleviating renal fibrosis." (PMID 39438470, 2024).
Alzheimer disease (1 paper, 2013). A progressive, neurodegenerative disease characterized by loss of function and death of nerve cells in several areas of the brain leading to loss of cognitive function such as memory and language. "Tau, an Alzheimer's disease associated protein, has been reported to be SUMOylated by SUMO-1, and to a much lesser extent by SUMO-2 or SUMO-3 simultaneously." (PMID 23382880, 2013).
breast carcinoma (1 paper, 2017). "Furthermore, HIDEEP reveals that doxorubicin directly targets TOP2A, one of breast cancer-causing genes, and dexamethasone has impacts on TOP2A through HEPs such as ANXA1 → SUMO3 → TOP2A and NR0B1 → UBC → TOP2A." (PMID 29192270, 2017).
chronic kidney disease (1 paper, 2024). Impairment of the renal function secondary to chronic kidney damage persisting for three or more months. "In patients with chronic kidney disease, we found a loss of Sumo3 expression, and it was highly related to LKB1 repression." (PMID 39438470, 2024).
Endotoxemia (1 paper, 2023). "Endotoxemia induced similar hyperkalemia and creatinine levels in wild-type and SUMO3-null mice, but the latter had higher HAGMA and blood urea nitrogen." (PMID 37520526, 2023).
fibrosarcoma (1 paper, 2017). A malignant mesenchymal fibroblastic neoplasm affecting the soft tissue and bone. "Arc was ectopically expressed in HT-1080 fibrosarcoma cells together with His6-tagged SUMO1, SUMO2, or SUMO3." (PMID 28553222, 2017).
Hyperkalemia (1 paper, 2023). An abnormally increased potassium concentration in the blood. "Of note, hyperkalemia and creatinine levels mimicked TNFα responses, but not in SUMO3-null mice as they had similar TNFα responses than wild-type mice, but higher HAGMA and blood urea nitrogen." (PMID 37520526, 2023).
melanoma (1 paper, 2020). A malignant, usually aggressive tumor composed of atypical, neoplastic melanocytes. "The resulting network with gene expression fold-change information indicated that SUMO3 gene and most of its interactors are up-regulated in invasive melanoma when compared with non-invasive melanoma." (PMID 32079144, 2020).
myocardial infarction (1 paper, 2022). Gross necrosis of the myocardium, as a result of interruption of the blood supply to the area, as in coronary thrombosis. "Sumo3 from GO assay has been reported to mediate cardiomyocyte apoptosis and myocardial infarction." (PMID 35544480, 2022).
infection (14 papers, 2011 to 2024). The state of being infected such as from the introduction of a foreign agent such as serum, vaccine, antigenic substance or organism. "It has been reported that infection with TuMV results in upregulation of SUMO3 expression and the interaction between SUMO3 and NIb is necessary for successful infection." (PMID 36631662, 2023). "In contrast, RanGAP1, a cellular protein that is constitutively modified by both SUMO1 and SUMO3, remained unchanged during infection." (PMID 26814176, 2016). "We show that TFII-I is targeted by E4-ORF3 for modification with both SUMO1 and SUMO3 and that these modifications are reduced at later times during the course of infection." (PMID 26814176, 2016). "In addition, SUMO3 (small ubiquitin-like modifier 3) dynamically regulates turnip mosaic virus (TuMV) infection and plant immunity through sumoylation of NIb and NPR165." (PMID 37230965, 2023). "SUMO3 ligates to replication protein NIb to facilitate turnip mosaic virus (TuMV) infection." (PMID 32866188, 2020). "It was recently reported that during infection, SUMO-1 localizes outside RCs, whereas SUMO-2 and SUMO-3 are mainly detected inside RCs." (PMID 32184235, 2020). "Taken together, these results show that early post-infection, EMCV enhanced PKR-SUMO1 and PKR-SUMO3 modified forms that were decreased later only in SUMO3-expressing cells." (PMID 29352251, 2018). "To demonstrate that EMCV enhanced PKR conjugation to SUMO3 2 h post-infection and decreased PKR-SUMO3 modified forms 4 h post-infection, we performed Ni-NTA purifications in extracts from His-SUMO3 expressing cells uninfected and infected with EMCV for 2 h or 4 h." (PMID 29352251, 2018). "Wild-type Ad5 infection induces SUMO1 and SUMO3 modification of TFII-I." (PMID 26814176, 2016). "In addition, we show that overexpression of SUMO3 in HeLa cells induced PKR SUMOylation, reduced its phosphorylation and the phosphorylation of eIF-2α upon transfection with poly(I:C) and infection with EMCV or VSV at an MOI of 0.2 without affecting the PKR protein level." (PMID 29352251, 2018).
cancer (5 papers, 2021 to 2025). A tumor composed of atypical neoplastic, often pleomorphic cells that invade other tissues. "Several cancer-associated mRNAs were found using the RISCTRAP assay, including ICAM1, SUMO3, HIF1A, and SEC23A." (PMID 34831007, 2021). "For this reason, SUMO2, SUMO3 and SUMO4 can be potentially exploited in further anti-cancer mechanisms investigations (p-value = 0.024 in the present study), in order to shed light on the regulatory mechanisms underlying the activity of SUMO machinery in an oncogenic framework." (PMID 35741808, 2022).
tumor (1 paper, 2022). "In contrast, the expression level of SUMO3 was positively correlated with the tumor infiltration levels of various immune cells and with the expression of most immune modulators." (PMID 36589239, 2022). "The results showed that SUMO1/2 and SUMO3 played opposite roles in PAAD immune regulation, indicating that the roles of SUMO family members in PAAD tumor immune regulation are diverse and complex." (PMID 36589239, 2022).
SUMO3 also shares sentences with these, for which no sentence is quoted: amyotrophic lateral sclerosis (1 paper); Anxiety (1); autosomal dominant polycystic kidney disease (1); brain ischemia (1); cardiomyopathy (1); diabetic kidney disease (1); emphysema (1); HIV-1 infection (1); Infertility (1); kidney diseases (1); lung adenocarcinoma (1); metabolic disease (1); osteosarcoma (1); Parkinson disease (1); Stroke (1).